BNIP3 (BCL2 interacting protein 3)
Diseases named in the same sentence as BNIP3 in open-access papers (continued):
Sharing a sentence is not in itself a finding about the gene and the disease.
tumor (continued). "Considering that tumor microenvironment could be related to altered metabolism, we evaluated the expression of glutamine metabolism-related proteins and amino acid transporter proteins according to BNIP3 status." (PMID 33505538, 2021). "Other reports have shown that increased expression of BNIP3 detected in hypoxic regions of lung and prostate cancers, glioblastoma multiforme, cervical tumors, endometrial cancer, breast carcinomas and gastric adenocarcinomas correlates with an aggressive tumor phenotype and a poor prognosis." (PMID 35201480, 2021). "Thus, the role of BNIP3 in tumor progression and resistance to therapy remain highly context-dependent and could provide both tumor suppressing and tumor promoting mechanisms." (PMID 33207677, 2020). "It is frequently found that the high expression of BNIP3 that occurs in many kinds of malignancies, such as salivary gland adenoid cystic carcinoma, endometrial cancer, DCIS of breast and cervical cancer is associated with the aggressiveness of the tumor and poor prognosis." (PMID 32587855, 2020). "However, it is worth mentioning that radical inhibition of BNIP3 may decrease its levels in both normal and benign tumor tissues, resulting in ambiguous cell fate." (PMID 33207677, 2020). "Indeed, in melanoma, downregulation of BNIP3 led to a significant reduction of cell migration activity and vascular mimicry by remodeling the cytoskeletal actin configuration, attenuating the aggressive behavior of the tumor." (PMID 33207677, 2020). "Low BNIP3 levels might maintain cell death resistance and the survival of tumor cells." (PMID 33207677, 2020). "For instance, loss of BNIP3 in a mouse model of mammary tumorigenesis reduces mitophagy and increases mitochondrial ROS levels, which results into increased normoxic HIF-1α stabilization, eventually promoting the Warburg effect and subsequently tumor progression." (PMID 31121959, 2019). "Furthermore, glycolysis and angiogenesis are increased in tumors forming in BNIP3 null mice, indicating the negative association of BNIP3 with significant biological processes that are required for tumor cell growth." (PMID 28968982, 2017). "In early phases of cancer development BNIP3 acts as a tumor suppressor, preventing ROS-related DNA damage to protect cells from malignant transformation; while in later stages, mitophagy allows tumor cells survival under stress conditions like hypoxia, contributing to chemoresistance." (PMID 29207653, 2017). "However, the role of BNIP3 in tumor progression remains controversial." (PMID 28968982, 2017). "In response to low oxygen levels, tumor cells adapt by activating HIF-1 and its downstream target genes, such as BNip3 and BNip3L." (PMID 40129974, 2025). "High expression of EUDAL facilitates sustained phosphorylation of EGFR in hypoxic tumor cells and subsequently activates downstream STAT3/BNIP3 signaling, which leads to autophagy-related drug resistance." (PMID 40940319, 2025). "PCS inhibited the expression of TOMM20, and improved the expression of Bnip3, Cytoc as well as the conversion of LC3‐I to LC3‐II, which collectively emphasised the promotion of mitophagy in tumour‐conditioned RAW264.7 cells after PCS treatment." (PMID 40604335, 2025). "The PINK1/Parkin activator enhances treatment sensitivity and reduces tumor growth and metastasis, while the BNIP3/NIX inhibitor promotes cell survival and drug resistance, facilitating tumor progression." (PMID 41551160, 2025). "RT-qPCR and Western blot analyses revealed that, compared to the sh-NC group, the sh-SIRT1 group had significantly lower expressions of BNIP3, PINK1, and PRKN and their corresponding proteins in the tumor tissues." (PMID 39266959, 2024). "It’s found that IHC signals of BNIP3, CYCS, RRAGD, CD44, EIF4E, and MAP4K1 were consistently high in tumor cells of HCC, compared with normal tissues, implying that these genes were indeed ectopically expressed in HCC." (PMID 38468074, 2024).
tumor (continued). "miR-1290 levels of tumor and stromal was positively correlated with stromal α-SMA, whereas in the stroma, a strong correlation between α-SMA and BNIP3." (PMID 38825680, 2024). "BNIP3 and NIX are two crucial proteins mediating mitochondrial autophagy and play roles in tumor development." (PMID 39763653, 2024). "Dysregulation of mitophagy, involving proteins such as Parkin, PINK1, BNIP3, BNIP3L/NIX and p62/SQSTM1, further exacerbates tumour growth and metastasis by fueling cancer cell energy demands and enhancing cell survival through anti‐apoptotic pathways." (PMID 38534098, 2024). "Results showed that the mRNA levels of BNIP3, CYCS, RRAGD, CD44, EIF4E, MAP4K1, and LIN28B were higher in tumor samples, whereas the mRNA levels of PPARGC1A and FLT3 were higher in normal samples." (PMID 38468074, 2024). "An increase in the expression of autophagy-related proteins (e.g., LC3, BNIP3 and p62) was also demonstrated in CCD-18-co-cultured tumor cells." (PMID 36835075, 2023). "Increased BNIP3 levels may be associated with tumor hypoxia and negative regulation of apoptosis." (PMID 37749074, 2023). "The results of this study in vivo and in vitro show that the overexpression of BNIP3 can promote the proliferation of DLBCL cells, promote tumor growth, and inhibit cell apoptosis, increase the level of Bcl-2, and reduce Bax." (PMID 35783530, 2022). "PINK1, Parkin, BNIP3, NIX, and FUNDC1 have been reported to facilitate tumor progression and recurrence." (PMID 36207761, 2022). "BNIP-3 is a HIF-dependent gene product, and as such has a role in hypoxia-induced autophagy, which enables cancer cells to survive and enhance tumor progression." (PMID 36499465, 2022). "Several genes were found at lower expression levels in tumor cases, such as AXL, BAHC2, CFLAR, and DNMT1 while others were overexpressed such as BNIP3, DIABLO, FADD, and IDH1." (PMID 35911707, 2022). "In some studies, the transcription of BNIP3 and Nix was significantly up‐regulated under hypoxia, but Nix sensitivity to hypoxia was significantly reduced, and Nix expression was neither associated with the oxygen partial pressure in tumours nor activated by ischemia in brain cells." (PMID 36200262, 2022). "The Fuzheng Yiliu decoction can suppress liver metastasis in mice tumor growth; induce apoptosis of tumor cells; and activate Beclin1, Bnip3, and LC3 proteins of HCC cells (HepG2s), which induce the autophagy of tumor cells." (PMID 38094222, 2022). "Several studies have revealed that PINK1, Parkin, BNIP3, and NIX, the most important mitophagy receptors on the OMM, are tumor suppressor genes involved in promoting apoptosis, implying the positive correlation between mitophagy and apoptosis." (PMID 35581181, 2022). "In a mouse model of mammary tumorigenesis, inactivation of BNIP3 resulting in defective mitophagy was shown to elevate ROS production and normoxic HIF-1α stabilization, which accelerated tumor progression to metastasis." (PMID 34490076, 2021). "ULK1/2 is a known inhibitor of BCL2/adenovirus E1B 19 kDa interacting protein 3 (BNIP3) 27, the atypical BH3-only protein which functions as a tumor suppressor in human cancers 28-30." (PMID 34345207, 2021). "(I, J) Concordance between elevated transcription (UMI per million) of BNIP3 in RNA-seq (I) and (J) BNIP3 MFIs in (left) immunostained microcolonies and macrometastases populating the livers of 6419c5-YFP tumor-bearing mice (NμCol = 53, Nmacro = 60)." (PMID 33620315, 2021). "Besides the tumor-suppressing role, BNIP3-induced mitophagy could stimulate cancer progression." (PMID 33207677, 2020).
tumor (continued). "Both BNIP3 and STC1 are hypoxia-responsive genes, and their overexpression actuates tumor progression." (PMID 31212896, 2019). "Then, it was shown that BNIP3 is essential for hypoxia-induced autophagy in cancer cells and disruption of BNIP3 triggered cell death, which suggests a positive role of HIF-1α, BNIP3, and autophagy in tumor survival and progression." (PMID 31078780, 2019). "On the other hand, BNIP3 was mainly localized to the nucleus and less in the cytoplasm of laryngeal squamous cell carcinoma (SCC) tumor cells." (PMID 30250843, 2018). "BNIP3 and BIRC3, the other two up-regulated genes by IBTKα RNA interference, are tumour suppressors." (PMID 29317636, 2018). "We measured ascorbate, HIF-1α, and HIF-2α protein and HIF downstream targets BNIP3, CA9, cyclin D1, GLUT1, and VEGF (combined to generate the HIF pathway score) in VHL-defective ccRCC (n = 73) and VHL-proficient pRCC human tumor tissue (n = 41)." (PMID 30555801, 2018). "Synchronous with the changes in HIF/BNIP3/BCL-xL/VEGF/CXCR4 upon artificial miR-199a-5p overexpression, PC-3 and DU145 cells showed reduced growth, invasiveness and tumor angiogenic ability but increased apoptosis (as assessed by the TUNEL assay)." (PMID 29137361, 2017). "Autophagy undergoes both short- and long-term activation during cachexia; accordingly autophagy-related transcripts Bnip3, LC3b, GABARAPL1, Atg7, and CathepsinL were considerably increased in vehicle and (−)-JQ1-treated C26-tumor-bearing mice." (PMID 29167426, 2017). "In summary, we report that miR-199a-5p plays a tumor-suppressive role by directly targeting HIF-1α and thereby suppresses genes downstream of HIF-1α, such as VEGF, CXCR4, BNIP3 and BCL-xL." (PMID 29137361, 2017). "Tumor tissues from the mice treated with both YCW1 and IR showed lower BNIP3 and higher LC3 expression compared with the tumor tissues from mice treated with a single agent." (PMID 27286975, 2016). "The expression of BNIP3, a Bcl-2 family member, correlates with HIF-1α expression levels in various types of tumor cells." (PMID 26711814, 2015). "Consistent with their ability to induce cell death, BNIP3 and BNIP3L inhibit tumor growth especially in hypoxia conditions." (PMID 26432836, 2015). "Immunohistochemical staining of BNIP3, GLUT1, CAIX, VEGF-A and PHD2 was observed in the suprabasal portion of the overlying epidermis of the BCC and TE tumour islands and in the internal control, the HF." (PMID 25181405, 2014). "Both BNIP3 and NIX are deregulated in human cancer with elevated expression of both genes detected at pre-malignant stages of several different tumor types, but they appear to be down-regulated upon progression to invasive and malignant cancers." (PMID 24350057, 2013). "Several miR-143 targets, including DNMT3A and KRAS, and miR-145 targets including BNIP3, IRS, C-MYC, YES and STAT1, have been identified, indicating that miR-143 and 145 act as tumor suppressors to repress tumor proliferation or promote apoptosis." (PMID 22438992, 2012). "BNIP3 and TGM2 expression was scored as high or low, based on the number of tumor cells stained and the staining intensity." (PMID 22458929, 2012). "Positive expression of BNIP3 was mainly localized in the nucleus, with some expression detected in the cytoplasm of laryngeal SCC tumor cells." (PMID 22458929, 2012). "In this regard, further studies must be performed to check BNIP3 and BNIP3L status in the different tumour tissues." (PMID 20461082, 2010). "HLTF, BNIP3, H2AFX, CACNA1G, TGIF, ID4 and CACNA1A were identified as novel tumor suppressor candidates methylated in lung tumors." (PMID 20849603, 2010).
tumor (continued). "After the test, it was found that DNMT1 and HDAC1/2 in the tumor tissue were significantly downregulated, while the transcriptional levels of pro-apoptotic genes such as BAX, BNIP3, and APAF1 were significantly increased, and the tumor volume was significantly reduced." (PMID 41335282, 2025). "By single-cell analysis of various epithelial cancers, the predominant expression of BNIP3 occurs in epithelial cells within the tumor microenvironment, rather than in immune cells." (PMID 40337509, 2025). "PTBP2-mediated induction of autophagy through BNIP3 may provide CML cells with extra nutrients and promote further tumor progression." (PMID 40113750, 2025). "For instance, a tumor-suppressor function for BNIP3 has been suggested that is independent of its role as a BH3-containing protein." (PMID 38177312, 2024). "The FOXO transcription factor family, with tumor-suppressive functions in various cancers, is involved in apoptosis, triggering the expression of death receptor ligands like Fas ligand, TNF apoptosis ligand and Bcl-XL, bNIP3, and Bim from Bcl-2 family members." (PMID 39734333, 2024). "Specifically, studies on mitophagy-related proteins, such as those involved in the PINK1/Parkin and BNIP3/NIX pathways, offer potential avenues to modulate mitophagy levels, thereby influencing tumor cell survival and proliferation, and providing new hope for cancer treatment." (PMID 39611141, 2024). "Furthermore, we examined TET2, BNIP3, and BNIP3L protein levels in HCC-SR tumour tissues by performing immunohistochemical staining." (PMID 37005657, 2023). "MenSC treatment increased the levels of TET2, BNIP3, and BNIP3L in the Huh7-SR xenograft tumours." (PMID 37005657, 2023). "We found a significant increase in the expression of hypoxia-related genes such as HIF-1α, BNIP3, and CA-IX with an increase in the number of days of tumor spheroids development as compared to non-tumorigenic spheroids." (PMID 35837091, 2022). "Of note, BNIP3 is mostly expressed by epithelial cells, but not immune cells in the tumor microenvironment." (PMID 35912211, 2022). "BNIP3 and GOT1 were downregulated gradually with the increase in the grade, but RRM2 increased gradually with the increase in the grade and stage, which revealed that three target genes were closely related with tumor progression." (PMID 35350243, 2022). "The expression levels of BNIP3 and GOT1 decreased gradually with the increase in grades, but RRM2 increased gradually with the increase in clinical grades and stages, which revealed that three target genes were closely related to tumor progression." (PMID 35350243, 2022). "Although BNIP3 is a potential target of ULK1, decreased BNIP3 protein levels in STAT3‐KO and mutant expressing cells indicate that BNIP3 is degraded by ULK1‐dependent autophagy, a mechanism found to decrease BNIP3 protein levels in tumour cells." (PMID 35670018, 2022). "Moreover, sh-BNIP3 resulted in diminished expression of BNIP3 and LC3 in tumor tissues of nude mice." (PMID 35200106, 2022). "Thus, the obtained results demonstrate that under hypoxic conditions, BNIP3 and BNIP3L can rescue tumor cells treated with antitumor drugs by executing mitophagy." (PMID 34439183, 2021). "According to a study, both mir-148b and mir-152 can reactivate some tumor suppressor genes such as SPARC and BNIP3 by targeting DNMT-1, thereby resulting in modification of methylation status of the mentioned tumor suppressor genes and reducing tumorigenic properties in pancreatic cancer cell lines." (PMID 33632341, 2021).
tumor (continued). "Moving forward, it will be informative to determine to what extent the beneficial effects of ULK-101 in preventing tumor growth are due to specific effects on mitophagy and BNIP3 levels as opposed to more general effects on overall autophagy." (PMID 34654847, 2021). "Consistent with the apparently inhibitory effect of Mdivi-1 on tumor growth, mitophagy-related proteins DRP1, BNIP3, and LC3B expression were significantly reduced, and apoptotic proteins Bax and cleaved caspase-3 expression were significantly increased in the Mdivi-1 treatment group." (PMID 32661251, 2020). "Furthermore, oxidative stress in tumor cells induces the activation of pro-autophagy factors, such as LC3, BNIP3L, ATG16L, BNIP3, NF-κB, and HIF-1α, which promote the degradation of caveolin-1 (Cav-1), leading to autophagy activation." (PMID 32707662, 2020). "At the same time CD44+ and CD44− tumor cells did not express BNIP3, while CD44− xenografts were enriched in CD31+ cells." (PMID 32214151, 2020). "Moreover, in tumor cells, NIX and BNIP3 regulate mitophagy in response to hypoxia, and the deregulation of NIX and BNIP3 expression is associated with increased tumor growth." (PMID 30669284, 2019). "In the C26-bearing mice, exercise did not change PINK1 levels as compared to sedentary tumor hosts and BNIP3 levels remained comparable to controls." (PMID 30823492, 2019). "BNIP3 acted as tumor suppressor and alleviated FTO-dependent tumor growth and metastasis." (PMID 30922314, 2019). "Since BNIP3 and NIX are both involved in mitophagy and apoptotic cell death, it is possible that their role may vary depending on the tumor type." (PMID 30250843, 2018). "This is probably due to the reduced sensitivity of the tumor cells that were BNIP3 negative to the induction of apoptosis." (PMID 28968982, 2017). "Besides mTOR, HIF-1α plays a crucial role by upregulating its targets expression, BNIP3 and BNIP3L, to activate autophagy in tumor cells." (PMID 28729825, 2017). "Contrary to BNIP3, the role of NIX and FUNDC1 in tumor progression remains relatively unknown, requiring further investigation." (PMID 28932704, 2017). "The expression levels of BNIP3 were higher in the non-tumor (NT) tissues compared with the tumor (T) specimens." (PMID 28968982, 2017). "Among them BNIP3 (down-regulated in HD-MM), a downstream target of NUPR1, is a novel hypoxia-inducible pro-apoptotic mitochondrial member of the Bcl-2 family which acts as tumor-suppressor by regulating apoptosis in normal and malignant cells." (PMID 26056083, 2015). "Previous studies have reported that mitochondrial autophagy induced by hypoxia requires the HIF-1-dependent expression of BNIP3, which plays a protective role by disrupting the Bcl-2-Beclin1 complex without inducing cell death in tumor cells." (PMID 25383959, 2014). "In 6/15 (40%) of cases where tumor cells had a very low signal or no BNIP3 expression, the normal breast tissue showed more BNIP3 expression than the tumor cells." (PMID 19505343, 2009). "This suggests that tumour cells that do not express BNIP3 have a growth advantage related to their ability to escape apoptosis induced by hypoxia." (PMID 15756280, 2005). "Overexpression of SIRT1 enhanced FOXO3 deacetylation and activity, promoting BNIP3 transcription and PINK1/Parkin-mediated mitophagy, which in turn promoted cell proliferation, migration, invasion, and inhibited apoptosis in vitro, as well as increased tumor growth and hormone resistance in vivo." (PMID 39266959, 2024).